TET2 (tet methylcytosine dioxygenase 2)
Diseases named in the same sentence as TET2 in open-access papers (continued):
Sharing a sentence is not in itself a finding about the gene and the disease.
prostate carcinoma (34 papers, 2013 to 2026). A carcinoma that arises from epithelial cells of the prostate gland. "Our study elucidated the distinct genetic basis of prostate cancer in the transition zone and identified TET2 mutation as an independent prognostic determinant in TZ PCa." (PMID 40297177, 2025). "TET2 was also significantly associated with prostate cancer risk (OR = 3.31 [2.26–4.78], P = 1.71 × 10−9)." (PMID 39971927, 2025). "TET2, which is a critical gene involved in androgen receptor (AR) signaling exhibits reduced expression in prostate cancer and is associated with adverse clinical outcomes, including elevated Gleason scores and increased metastatic potential." (PMID 40297177, 2025). "Downregulation of TET2 mRNA in prostate cancer was found to be strongly associated with reduced survival." (PMID 38515066, 2024). "Phosphatidylethanolamine synthesis in non-small cell lung cancer is significantly enhanced by ETNK2, whereas reduced ETNK2 expression in prostate cancer results from the loss of TET2 targeted demethylation." (PMID 35873461, 2022). "It has been reported that TET2 binds the androgen receptor and its loss is associated with prostate cancer." (PMID 32226005, 2020). "The master methylation regulator TET2 is downregulated in prostate cancer, where its loss is linked to aggressive disease and poor outcome." (PMID 33008340, 2020). "A prostate cancer variant (rs7679673 in TET2) was specifically associated with a lower risk of DLBCL." (PMID 24598796, 2014). "Among men carrying two A alleles at rs7679673 in TET2, the risk of prostate cancer associated with high aldrin use was 3.67 times those with no use (95% CI: 1.43, 9.41) (P-interaction = 0.006)." (PMID 23593118, 2013). "Interestingly, TET2, an enzyme that catalyzes DNA demethylation, is a tumor suppressor in prostate cancer and is frequently mutated, with loss of TET2 expression associated with cancer progression and reduced patient survival." (PMID 41602415, 2026). "Thus, we searched for germinal variants in ASXL1, CHD1, IDH1, SETD2 and TET2 epigenetic genes in Polish prostate cancer patients and controls and analyzed the impact of them on disease clinical course, including overall survival time." (PMID 39529133, 2024). "The results provided in this study are applicable to studies of TET2 in human cancers and may explain some of the previous SNP associations, such as rs7679673 of TET2 correlating with a family history of prostate cancer." (PMID 31231651, 2019). "Moreover, recent genome-wide association studies in prostate cancer tissues have demonstrated that TET2 variation is genetically correlated with the development of prostate caner and metastasis." (PMID 28783103, 2017). "Importantly, miR-29a/b target ten–eleven translocation 2 (TET2), an enzyme that catalyzes the oxidation of methylated cytosine (5-mC) to 5-hydroxymethylated cytosine (5-hmC), an epigenetic hallmark of prostate cancer progression." (PMID 28783103, 2017). "At the gene level, we also identified TET2 and DMD to be associated with the risk of prostate cancer." (PMID 39971927, 2025). "Androgens and androgen receptors (AR) play key roles in prostate cancer development, and TET2 physically interacts with AR and its coactivators to affect AR signaling." (PMID 40599235, 2025). "In turn, TET2 is inhibited by AR in prostate cancer cells through two pathways: AR‐induced inhibition of TET2 expression by the miR‐29 family, and direct binding of AR to the enhancer region of TET2 and inhibition of its transcription." (PMID 40599235, 2025). "Other prostate cancer-associated somatic mutations were consistent in some PDOs and parental tumours, such as BRCA1, ALK, STED2, TET2, TRPM8, AURKA, ERBB2, GATA2." (PMID 41403018, 2025). "In the NASA Twins Study, both career astronauts had increased mutational burden in epigenetic regulators such as DNMT3A and TET2 compared to prostate cancer patient controls." (PMID 38634106, 2024).
prostate carcinoma (continued). "Patient 2 presented with a history of prostate cancer treated with radiation therapy and AML with normal cytogenetics and CEBPA (monoallelic), CSF3R, and TET2 mutations." (PMID 36077629, 2022). "ALYREF, DNMT1, and TET2 were involved in the cell cycle, DNA replication, and prostate cancer-related pathways." (PMID 34325709, 2021). "In gastric cancer, FENDRR affects cell malignant activity via the miR-214-3P/TET2 axis, whereas in prostate cancer, it reduces malignancy by competitively binding miR-18a-5p with Runt-related transcription factor 1 (RUNX1)." (PMID 34621665, 2021). "Overall, this model integrates both genomic expression data and epigenomic regulation by selecting candidate genes governed by TET2 in prostate cancer." (PMID 33008340, 2020). "TET2 inhibition and decreased 5hmC levels activate key prostate cancer‐related pathways, including the mechanistic target of rapamycin kinase (mTOR) and AR pathways, which drive prostate cancer development." (PMID 40599235, 2025). "It was reported that TET-2 could regulate the global hydroxymethylation status and further participate in tumor progression in prostate cancer." (PMID 35965615, 2022). "Decreased TET2 expression has been reported in solid malignant tumors, such as thyroid, gastric, colorectal, ovarian, breast, and prostate cancers." (PMID 35223782, 2022). "Notably, another study also observed the importance of TET2 in prostate cancer by regulating AR activity." (PMID 28783103, 2017). "This SNP is located between two gene regions, TET2, a gene recently characterized as a tumor suppressor gene involved in the pathogenesis of several hematopoietic diseases, and PP2A, a gene implicated in androgen regulation in prostate cancer cell lines." (PMID 23593118, 2013). "However, perhaps due to its low somatic mutation rates in primary prostate cancer, TET2-mediated changes have not been systematically investigated as potential drivers of cancer development." (PMID 30917865, 2019). "The tumor-suppressive TET enzymes, which are involved in DNA demethylation, are decreased in prostate cancer (PCa); in particular, TET2 is specifically targeted by androgen-dependent mechanisms of repression in PCa and may play a central role in carcinogenesis." (PMID 30917865, 2019). "Among men carrying two A alleles at rs7679673 in TET2, the risk of prostate cancer associated with low aldrin use was 1.86 times those with no use (95% CI: 0.73, 4.75) and for high aldrin use was 3.67 times those with no use (95% CI: 1.43, 9.41) (P-interaction = 0.006)." (PMID 23593118, 2013). "In prostate cancer, the androgen receptor decreases the expression of miR-29b which targets both TET2 and 5-hmC; 5-hmC represses FOXA1 activity, while its reduction activates the mTOR pathway and AR of prostate cancer." (PMID 29850477, 2018).
myeloid leukemia (31 papers, 2015 to 2025). A clonal proliferation of myeloid cells and their precursors in the bone marrow, peripheral blood, and spleen. "Within the UKBB, a GWAS for ICD-10 code C92 Myeloid leukaemia showed the strongest association with pLoF variants in the genes TET2 (P = 1.53e−25, β = 0.176629), EZH2 (P = 1.53e−8, β = 0.430923), and CHEK2 (P = 5.78e−7, β = 0.092176)." (PMID 40335619, 2025). "Evidence suggests that TET2 mutations also affect prognosis in myeloid leukemia and other hematopoietic malignancies." (PMID 40116537, 2025). "TET2 mutations affect prognosis in myeloid leukemia and other hematopoietic malignancies, but little is known about their impact on solid tumors." (PMID 40116537, 2025). "Loss of function of TET2 has been reported in myeloid leukemia due to splice site mutations, out-of-frame insertions or deletions, and base substitutions." (PMID 38769532, 2024). "Mutations in ATM, MGA, KMT2A, MLLT10, NSD1, and TET2 have been commonly identified in several hematological neoplasms, including both acute lymphoid and myeloid leukemia." (PMID 38672648, 2024). "Combined heterozygous loss of Tet2+/– and Dnmt3a+/– and expression of Flt3ITD/WT results in a transplantable myeloid leukemia." (PMID 36073548, 2022). "Since TET2 mutations are associated with higher response rate to demethylating agents in myeloid leukemias, it is reasonable to investigate the role of demethylating agents in patients with TET2 mutated MALT lymphomas." (PMID 35008340, 2021). "Intriguingly, whereas Tet2-deficient mice develop myeloid leukemia, dual Tet1/Tet2 deficiency resulted instead in the development of B cell lymphoma with delayed disease progression (12–15 months) compared to Tet2 deficiency alone." (PMID 28408905, 2017). "Together these data show that acute deletion of Tet3 in a Tet2-deficient context, or concurrent deletion of both Tet2 and Tet3, leads to the rapid cell-autonomous induction of an aggressive, transplantable myeloid leukaemia in mice." (PMID 26607761, 2015). "Some studies have indicated that Tet2 may play a key role in shaping myeloid cell plasticity because of its high expression in these cells and its frequent mutation in myeloid leukemias." (PMID 34222235, 2021). "Acute inducible Tet2/Tet3 DKO in HSCs causes the rapid emergence of aggressive myeloid leukemia." (PMID 33184433, 2020). "In mice, Tet2 deletion causes myeloid leukemia after a long duration." (PMID 33184433, 2020). "We further propose that loss of TET2 may sensitize myeloid leukemia cells to DNA repair stress, such as is induced by treatment with PARP inhibitors." (PMID 31001476, 2019). "Based on our review of the literature, we provide a new hypothesis that loss of TET2 may lead to dysregulation of the DNA repair response, augment genome instability, and subsequently sensitize myeloid leukemia cells to PARP inhibitor treatment." (PMID 31001476, 2019). "Based on our review of the literature, we hypothesize that loss of TET2 might sensitize myeloid leukemia cells to poly (ADP-ribose) polymerase inhibitors (PARPis)." (PMID 31001476, 2019). "In addition, key enzymes in maintaining DNA methylation balance, such as DNA methyltransferase 3A (DNMT3A) and Ten-Eleven-Translocation 2 (TET2), are frequently mutated in myeloid leukaemia, reinforcing the importance of DNA methylation in myeloid differentiation." (PMID 31799621, 2020). "Recently, it was hypothesized, that TET2, which is frequently mutated in hematologic malignancies, maintains genomic stability via promotion of DNA damage repair and that loss of TET2 might sensitize myeloid leukemia cells to PARP inhibitors." (PMID 31555628, 2019). "However, the mechanism by which TET2 mutations cause myeloid leukaemia is unclear." (PMID 28130413, 2017).
myeloid leukemia (continued). "Aberrant DNA methylation mediated by mutations of TET2, WT1, DNMT1, DNMT3A, and DNMT3B genes is correlated to the pathogenesis of myeloid leukemia." (PMID 37375831, 2023). "We found a myeloid leukemia signature was also enriched in Tet2-KO HSCs relative to WT at steady state and upon IL1β stimulation." (PMID 38062031, 2023). "In contrast, a recent study in AML patients showed a positive correlation between TET2 and TET3 and KO of both TET2 and TET3 in hematopoietic precursor cells in mice resulted in an almost complete loss of 5hmC and the emergence of myeloid leukemia." (PMID 36059621, 2022). "Combined heterozygous loss of Tet2 (Tet2+/–) and Dnmt3a (Dnmt3a+/–) and expression of Flt3ITD/WT (Tet2+/– Dnmt3a+/– Flt3ITD/WT) results in an aggressive lethal myeloid leukemia." (PMID 36073548, 2022). "In contrast, acute inducible deletion of both Tet2 and Tet3 in hematopoietic stem cells resulted in the rapid emergence of an aggressive myeloid leukemia with 100% penetrance in only 4 weeks." (PMID 28408905, 2017). "Mice deficient in TET2 alone were similarly viable, but about a third developed malignancies resembling myeloid leukemia, indicating the significance of TET2 in hematopoiesis." (PMID 26989192, 2016). "Although most mice that received transplant with TET2 KO cells succumbed to myeloid leukemia, with a median latency of 104 days, only 1 of 12 mice that received PROSER1 KO cells showed signs of distress and was observed to have transduced cells in the BM and spleen at the time of harvest." (PMID 40554416, 2025). "In mouse model studies, Asxl1 along with Tet methylcytosine dioxygenase 2 (Tet2) mutation initiated MDS-like hematopoietic impairment, and concurrent oncogenic mutations such as Kras and Nf1 accelerated the development of myeloid leukemia." (PMID 35682627, 2022). "To test whether TET inhibition by Epag imposes growth restrictions, particularly on TET2 knockout myeloid leukemia cells compared with WT cells, we tested isogenic THP1TET2KO cells generated using CRISPR-Cas9 and treated with increasing doses of Epag." (PMID 35085104, 2022). "Recently, Tet2 has been hypothesized to enhance the sensitivity of myeloid leukemia cells to poly (ADP-ribose) polymerase inhibitors (PARPis)." (PMID 34222235, 2021). "Somatic alteration of TET2, TET1/TET2 deficiency (TET1/2 double knockout), and TET2/TET3 disruption (TET2/3 double knockout) can lead to a wide range of myeloid and lymphoid malignancies, late-onset B-cell lymphoma, and rapid and fully penetrant myeloid leukemia." (PMID 35429301, 2022). "An alternative hypothesis, not mutually exclusive, is that TET2 mutations predispose to multiple types of hematopoietic cancers, with myeloid leukemia is the most prominent and rapidly occurring." (PMID 28408905, 2017). "In previous studies, we and other laboratories have reported numerous TET2- and PTPN11-related murine models of myeloid leukemia." (PMID 35771283, 2022). "Curiously, however, mice lacking Tet1 alone, or both Tet1 and Tet2, developed B cell rather than myeloid leukemias with relatively long latency (12–15 months)." (PMID 28408905, 2017). "Tet1 behaves as a weak tumor suppressor in B cells but may be weakly oncogenic in HSPC, where it promotes the development of myeloid leukemia in the absence of Tet2." (PMID 28408905, 2017).
diabetes (30 papers, 2016 to 2025). "The TET2 rs2454206 genetic variant has also been reported to correlate with diabetes, and mice experiments suggest that TET2 loss-of-function-driven clonal hematopoiesis can contribute to insulin resistance and type 2 diabetes." (PMID 36009574, 2022). "Tet2 has also recently been associated with the glucose-AMPK-TET2-5hmC axis signaling pathway, linking the level of extracellular glucose to the dynamic epigenetic regulation of 5hmC with implications in diabetes and cancer." (PMID 34738906, 2021). "Furthermore, patients with bone marrow syndrome who also have diabetes exhibit a higher mutation rate of the 10-11 translocation 2 (TET2) and splicing factor 3b subunit 1 gene (SF3B1), which correlates with a more severe prognosis." (PMID 39926430, 2025). "Individuals with diabetes and an HbA1c level of approximately 10% exhibited reduced levels of 5hmC compared to healthy controls, a finding attributed to the destabilization of TET2 caused by hyperglycemia." (PMID 40599550, 2025). "TET2 mutation associated clonal hematopoiesis is also reported to aggravates insulin resistance in mice, establishing a causal relationship between TET2 mutation and type 2 diabetes mellitus." (PMID 34576030, 2021). "Thus, the ability of TBK1 to negatively regulate AMPK can be critical for reducing TET2 and associated epigenetic changes during the progression from pre-diabetes, overt diabetes, and cancer." (PMID 30791439, 2019). "TET2 and SF3B1 mutations have been found to present more frequently in the blood cells of MDS patients who also have diabetes." (PMID 40336178, 2025). "In individuals with bone marrow syndrome, mutations in TET2 and SF3B1 genes are associated with a more severe prognosis, and the presence of diabetes also amplifies the frequency of these genetic alterations." (PMID 39926430, 2025). "TET2 expression is upregulated in patients with diabetes and enables epigenetic changes, including reduced promoter DNA methylation, through a series of oxidative reaction." (PMID 38172938, 2024). "Studies have shown that under the high glucose conditions in patients with diabetes, the oxidative activity of TET2 increases, decreasing promoter methylation in retinal cells." (PMID 38172938, 2024). "In diabetes, TET2 can regulate the expression of ROBO4 and its downstream proteins by mediating active demethylation of the ROBO4 promoter, which accelerates the development of retinal vasculopathy." (PMID 37430272, 2023). "A pathway linking diabetes to cancer was revealed through the definition of a novel ‘phospho-switch’ that regulates TET2 stability and a regulatory pathway that links glucose and AMPK to TET2 and 5hmC." (PMID 37344841, 2023). "Recent studies have revealed that the TET2 phosphorylation pathway mediated by the energy receptor adenosine monophosphate-activated protein kinase (AMPK) plays an important role in linking diabetes and cancer." (PMID 35480097, 2022). "The Tet2-KO mice had a markedly reduced incidence of diabetes (median survival undefined) compared to WT recipients of NOD WT BM (median survival = 11 weeks) (p < 0.0001)." (PMID 34417463, 2021). "Intriguingly, hyperglycemia suppresses AMPK activity and destabilizes TET2, providing a possible mechanism linking diabetes and cancer." (PMID 34109280, 2021). "Here we show that Tet2 regulates pathologic interactions between β cells and immune cells in humans with immune infiltrates in the pancreas and with diabetes and in mice with autoimmune diabetes by controlling damaging inflammatory pathways." (PMID 34417463, 2021). "The Tet2-KO BM recipients developed diabetogenic T cells since splenocytes were able to transfer diabetes to NOD/scid recipients at a rate similar to WT cell donors." (PMID 34417463, 2021). "In diabetes, enzyme activities of both Dnmts and Tets are increased in the retina and its vasculature, and among these two families of enzymes, Dnmt1 and Tet2 are the only respective isoforms that are upregulated." (PMID 31277234, 2019).